CD44 (CD44 molecule (IN blood group))
Diseases named in the same sentence as CD44 in open-access papers (continued):
Sharing a sentence is not in itself a finding about the gene and the disease.
cancer (continued). "The binding of HA to CD44 has been shown to stimulate concomitant activation of a number of oncogenic pathways and abnormal cellular processes in cancer cells and cancer stem cells (CSCs)." (PMID 27070574, 2016). "In this study, HA-PEI conjugate was designed for delivery of miR-223 duplex to macrophages due to the high capacity of PEI for encapsulation of nucleic acids and targeting ability of HA to CD44-overexpressed cancer cells and macrophages." (PMID 27148749, 2016). "We previously discovered that the overexpression of miR-494-3p in aldehyde dehydrogenase 1 (ALDH1)+ CD44+ HNC-TICs inhibited their cancer stemness." (PMID 27399693, 2016). "Western blotting revealed high protein level of CD44, a cancer stem cell marker, in CEA−/lo CRC cells." (PMID 27813496, 2016). "The most ubiquitous, CD44 standard, has been used as a cancer stem cell marker in ovarian and other cancers." (PMID 27253518, 2016). "Such genetic tools will allow dissecting CD44 functions in skin aging and in pathological situations such as skin hyperplasia and cancer." (PMID 27831556, 2016). "At the same time, the density of macrophages expressing M2 marker CD163 appears to be more closely related to CD44 expressing cancer cells." (PMID 27807511, 2016). "Our previous study has revealed the enrichment of HER2+/CD44+/CD24-/low cancer stem cell population in MCF7/C6 cells." (PMID 27036550, 2016). "Recently, CD44 expression level was reported to be correlated with PCa grade in prostate biopsy samples, and proteomics analysis showed that CD44+ cells had positive correlation with genes related to cancer proliferation and metastasis." (PMID 27447616, 2016). "Metastasis-specific isoforms of CD44 were first documented in a model of rat pancreatic adenocarcinoma (CD44v4–7 and CD44v6-7) and subsequently in other cancers." (PMID 27200096, 2016). "Gemcitabine derivatives loaded iron oxide magnetic nanoparticles with anti-CD44 antibody modification were constructed for the selective treatment of CD44-positive cancer cells." (PMID 27679576, 2016). "In functional studies, specific targeted knockdown of CD44 has been shown to impede cancer progression." (PMID 28000766, 2016). "Defining this interactive complex of ERM and CD44 provides opportunities for targeted therapies aimed at counteracting cancer MDR clinically." (PMID 26938523, 2016). "This provides rationale to utilize HA-conjugated nanoparticles to target CD44-overexpressed cancer cells." (PMID 27200096, 2016). "And common isoforms of CD44, which have been identified related to cancer metastasis, are the surface adhesion molecules." (PMID 27738347, 2016). "Binding of HA to CD44 has been shown to stimulate multidrug and metabolic transporters that are important in cancer drug resistance." (PMID 26938523, 2016). "Since we have determined all CD44 transcripts, it would be interesting to determine which of the many CD44 transcripts have a direct role in cancer cell stemness." (PMID 27505250, 2016). "Kaplan-Meier Plotter was performed to identify the prognostic roles of CD44 mRNA in these two cancers." (PMID 27323782, 2016). "Hyaluronic acid (HA) has been used for target-specific drug delivery because of strong affinity to CD44, a marker in which overexpressed in cancer cells and cancer stem cells." (PMID 27473554, 2016). "As far as we know, this is the first demonstration of targeting CD44 cancer cell populations by PIT in TNBC." (PMID 27302409, 2016). "CD44+CD133+ cells which represent cancer stem cells (CSCs) in GBC possess the potentials for self-renewal and differentiation, tumorigenicity, extensive proliferation and high recurrence of tumors." (PMID 27769047, 2016). "When CD44 and MMP-14 are co-expressed in various cancer cell lines, they stimulate cell migration after the soluble part of CD44 is shed from the cell surface." (PMID 27590006, 2016).
cancer (continued). "Further, CD44 targeting by monoclonal antibodies and blocking peptides has been established as a promising therapeutic approach for cancer." (PMID 27521214, 2016). "The results indicated that resistant cells have an increased proportion of CD44+/CD24− cells being enriched in cancer stem-like cells, mainly when NumbL is downregulated." (PMID 27613838, 2016). "Cell phenotype was evaluated following staining and flow cytometry analysis for the following surface antigens; cancer stem cell markers, CD44 and CD24." (PMID 27632425, 2016). "Studies have shown in breast and other cancers that CD44 contribute to its progression, correlates with advanced grade tumors and offer a potential prognostic and therapeutic target in such tumors." (PMID 27584160, 2016). "Hierarchical Cluster data suggests a much more complex situation of NOTCH1 and HES1 expression correlated with cancer stem cell marker CD44, ALDH1, Slug and SOX2." (PMID 27108536, 2016). "Accordingly, the remarkable decrease of cancer stem cell markers, CD44 and Oct-4, also reflected the synergistic inhibition of cancer stemness." (PMID 28036386, 2016). "Using fluorophore-conjugated antibodies, we set out to measure expression levels of the exosomal surface marker CD63 and other cancer-related proteins shown in our mass spectrometry analyses of exosomes, such as CD44 and CD47." (PMID 27819324, 2016). "The gene c-myc and CD44, frequently altered in human cancers, emerges as oncogenic transcription factors that integrates the cell cycle with cell adhesion, and the apoptotic pathways." (PMID 27448980, 2016). "CD44 has been shown to have important roles in cancer progression, particularly in cell adhesion, invasion, and migration." (PMID 27455311, 2016). "An intriguing cross talk between FGFR2 and CD44 likely maintains cancer stemness by reciprocally regulating their expression via differentially regulating c-Myc transcription." (PMID 27107424, 2016). "In this study hCpn10 was utilised as a novel protein scaffold for the display of peptides targeting Factor VIIa and the cancer marker CD44." (PMID 27874025, 2016). "Here we built upon this strategy to eliminate CD44 expressing cancer cells that include the CSC population, by using CD44 as a therapeutic target in a TNBC xenograft model." (PMID 27302409, 2016). "Studies have suggested that the percentage of CD44+/24–/low putative CSCs present would vary between cancer cell lines and this percentage is determined by two main factors: the origin of the cell line and the receptor status." (PMID 27229859, 2016). "Further western blot analysis revealed that the expression of cancer stem cell (CSC) associated markers Oct-4 and CD44 were elevated in drug-resistant cells compared with parental cells." (PMID 28036386, 2016). "A series of new studies indicated that CD44 expression was elevated in cancer stem-like cells in many kinds of cancer." (PMID 27323782, 2016). "Water soluble HA-DTX conjugate was prepared according to HA strong affinity for CD44, a cell surface protein which is overexpressed in many cancer cells and cancer stem cells." (PMID 27473554, 2016). "Our current knowledge indicates that HA promotes CD44 interaction with a number of intracellular regulators in a variety of cancer cells." (PMID 27070574, 2016). "MCF7/C6 cells are with enrichment of cancer stem-cell like cells with positive staining of CD44+/CD24-/low, OCT3/4 and NANOG." (PMID 27036550, 2016). "CD44 was well documented to be a common CSC marker in many cancers such as breast cancer, head and neck squamous cell carcinoma, pancreatic cancer, colon cancer, as well as OC, and proved to be correlated with therapeutic resistance." (PMID 27304054, 2016). "Up-regulation of the expression of CD44 a marker for stem cells of several types of cancer and the major hyaluronan receptor increases tumor growth and has an anti-apoptotic effect." (PMID 27340862, 2016).
cancer (continued). "For example, miR-328, a miRNA upregulated by GRA, inhibited cancer cell growth and impaired resistance to chemotherapeutic drugs by decreasing CD44 expression." (PMID 27713126, 2016). "CD44 has been characterized as a transmembrane glycoprotein and serves as a primary HA receptor in many cancer cells." (PMID 27070574, 2016). "As one of the most putative stem cell markers, CD44 plays a key role in many cellular processes, including cancer cell growth and migration." (PMID 26974151, 2016). "Hyaluronic acid (HA), a main component of the ECM, is a natural ligand to CD44 has been used as a targeting moiety for CD44 overexpressing cancers, facilitating preferential uptake and potent therapeutic efficacy." (PMID 27120809, 2016). "It represents the first human carcinoma for which a putative cancer stem cell subpopulation has been isolated on the basis of its CD44+/CD24−/low antigenic phenotype." (PMID 26556862, 2016). "On normal cells CD44 is mostly expressed in low affinity form showing less interactions with HA, while cancer cells express constitutive high affinity form of CD44." (PMID 27200096, 2016). "Of cancer stem cells (CSCs) markers, CD44 expression was effectively suppressed when FAM83D was knocked down by siRNA." (PMID 27769048, 2016). "Concerning CD44+ cells (cancer stem-like cells), we can notice an overexpression of Bcl-2 (+100%) and Bcl-XL, at a lesser extend (+20%)." (PMID 26934442, 2016). "Considerable research has indicated that MAPK-ERK signaling regulates CD44 expression in various types of cancer." (PMID 27623766, 2016). "The two new cell lines exhibited CD44+/CD49f+ and CD44+/EpCAM+ cancer stem cell (CSC) characteristics, and the EGF‐like domain of EpCAM was cleaved off." (PMID 26775583, 2016). "We found that CD44-IR700-mediated PIT treatment eliminated the bulk of CD44-positive cancer cells in the tumor." (PMID 27302409, 2016). "In another example of hCPn10 utility as a scaffold, CP7 bound to native CD44 overexpressed on cancer cells and bound rCD44 with high affinity (KD 9.6 nM)." (PMID 27874025, 2016). "Recently, the ability to exploit CD44 as a drug-delivery system in cancers, including breast has been investigated with encouraging results." (PMID 27379207, 2016). "Receptor (e.g., CD44) sensitivity to hyaluronan quantity and size provides a biosensor of the state of the microenvironment (inflammation, cancer stroma, or wound healing) surrounding the cell." (PMID 26904028, 2016). "Third, whole genome transcriptome analysis revealed that CEA−/lo cells preferentially expressed several genes including CD44, IGF1R etc., which were previously reported to associate with development and cancer stem cell functions." (PMID 27813496, 2016). "We then optimized the detection procedure to measure CD47 and CD44 levels in the circulating exosomes from human blood (cancer patients n = 60 and healthy controls n = 60)." (PMID 27819324, 2016). "A promising method for active targeting to cancer cells is the exploitation of the differential expression of CD44." (PMID 27120809, 2016). "Enriched SFCs in serum-free suspension culture exhibited cancer stem-like cell properties and increased single-positive CD44 + CD24-, stemness factor, mesenchymal marker expression ABC transporters and tumorigenicity in vivo compared with the parental cells." (PMID 27189061, 2016). "This way, we found 102 genes differentially expressed in CD24+ cancer cells compared to CD24+ normal breast epithelium cells, and 63 genes differentially expressed in CD44+ cancer cells compared to CD44+ normal breast epithelium cells." (PMID 26673618, 2016). "We demonstrated that VX2 tumors have higher expression of cancer stem cell markers such as AlDH1A1 and CD44 in comparison to normal rabbit liver cells." (PMID 26873175, 2016).
cancer (continued). "Signaling through CD44 involves the formation of complexes with various receptors which have also been involved in cancer, such as cMET, EGFR, HER2 and VEGFR, as well as the interaction with its main natural ligand, hyaluronic acid (HA)." (PMID 27463372, 2016). "At the same time, previous studies have also shown that inhibition of ERK decreases CD44 expression and cancer malignancy." (PMID 26769843, 2016). "CD44, one of the main Wnt/beta-catenin signaling target molecules as well as cancer stem cell marker molecules, is involved in acquisition of resistance to oxidative stress induced by the action of chemotherapeutic agents on the xCT transporter." (PMID 27412382, 2016). "The CD44 targeting approach developed here will be applicable not only to TNBC but to a wide range of cancers where CD44 is a significant target." (PMID 27302409, 2016). "Although CD44+ human carcinomas are very resistant to therapy and highly malignant, there is still some debate on the role of CD44 in CSCs." (PMID 27891093, 2016). "The AS events significantly altered in all three cancer types include many genes whose splicing was known to play critical roles in cancer development, such as the CD44, NUMB, and FN1." (PMID 25749525, 2015). "These researchers recently forced the expression of miRNA-328 in gastrointestinal cancer cell lines and found that CD44 expression was reduced, resulting in the repression of cancer cell growth in vitro and in vivo, and impaired resistance to ROS." (PMID 26273420, 2015). "In vitro and in vivo phase I and phase II clinical studies were initiated using ONCOFID-S in several CD44-overexpressing cancer cells, including colon, gastric, breast, esophageal, ovarian, and human lung cancer cells." (PMID 25999946, 2015). "Although overexpression of CD44 correlates with bad prognosis in patients with most human cancers, it was also found that CD44 is extremely sensitive to changes in the microenvironment." (PMID 25999946, 2015). "A more complete understanding of the mechanisms controlling how HA and CD44 mediate the stemness of CSCs will aid in the development of new treatment strategies to improve the outcome of cancer patients." (PMID 26322272, 2015). "CD44 was revealed to be a target of the Wnt pathway, which is accepted as a key pathway for the stemness maintenance of cancer stem cell markers." (PMID 26666511, 2015). "The HA-LIP conjugate can be used to deliver plasmid DNA and small interfering RNA (siRNA) to CD44 positive cancer cells." (PMID 25999946, 2015). "Several reports recently demonstrated that CD44 is present in lipid rafts, and the role of lipid rafts in cancer cell adhesion and migration is being elucidated." (PMID 26347743, 2015). "Recent experimental evidence from both in vitro clonogenic and in vivo tumorigenic assay revealed that CD44 (+) CRC cells display the properties of cancer stem cell, indicating a functional importance of CD44 in the CRC initiation and development." (PMID 26010608, 2015). "In all patient-derived cancer cells (8 patients) we found a reduction in E-Cadherin and an increase in the stem cell marker CD44 and TF protein upon exposure to platelets." (PMID 25886038, 2015). "It should be noted that all cells express CD44 in variable levels meaning both CD44lo and CD44hi cells exist within cancer cell lines and primary tumors." (PMID 26098778, 2015). "Through its interaction with the cell surface receptor, CD44, HA plays key regulatory roles in tissue homeostasis and cancer progression." (PMID 26005723, 2015). "By expressing both CD44 isoforms in c-Met + tumors, cancer cells are more likely to be resistant to standard treatment, metastasize, and colonize at distant organ sites." (PMID 25886575, 2015). "CD44 is a highly heterogeneous transmembrane glycoprotein that is involved in the growth and metastasis of many types of cancer, acting as a cellular adhesion molecule." (PMID 25658794, 2015).
cancer (continued). "Basal B cell lines, like MDA-MB-231 or SUM159PT have a mesenchymal-like phenotype and features of cancer stem cells (CD44+ CD24−/low, ALDH1+), indicating that Cyr61 is associated with a more aggressive phenotype." (PMID 25980494, 2015). "Gene expression levels of VIM and CD44 in MDA-MB-231 cancer cells were dramatically suppressed when the cells were grown in MEM in comparison to cells grown in DMEM." (PMID 25776572, 2015). "CD44 expression is an important prognostic marker in MM, as well as other cancers and cancer stem cells." (PMID 26429859, 2015). "It has also been reported that CD44 is involved in intracellular signaling through interactions with neighboring receptors, such as tyrosine kinase receptors, in many types of cancers." (PMID 25909162, 2015). "The cell morphology of the CD44+CD24−/lowESA+ cell should be further analyzed to provide a better basis for comparison of the cancer stem cell preferential adhesion among the different topographies." (PMID 25905435, 2015). "In view of IgG expression was highly correlated with CD44+/CD24−/low cells, we believe the IgG functions that promoting cancer genesis and metastasis are mainly association with CSCs of basal cell origin." (PMID 26472025, 2015). "Our laboratory and others have shown overexpression of the markers DclK-1, CD-44 and CD-133, representing cancer stemness, in PC." (PMID 25906749, 2015). "Since aggressive cancer cells highly express the CD44 receptor compared to normal cells, hyaluronic acid (HA) can be used for CD44 targeting molecule." (PMID 26163139, 2015). "Several stemness markers have been described for identification of BCSCs in cancer subtypes, such as CD44, CD24, CD133, EpCAM, CD166, Lgr5, CD47, ALDH1, and ABCG2." (PMID 26504780, 2015). "HA is the primary ligand for CD44, that is overexpressed in many cancer types including the ovarian histotype." (PMID 26097871, 2015). "As mentioned in the previous sections, the main property attributed to CD44 is its ability to bind HA, and this binding contributes to apoptosis resistance of cancer-initiating cells." (PMID 25999946, 2015). "CD44 is a particularly attractive target for this approach given its involvement in inflammation and cancer." (PMID 26379032, 2015). "Lipid rafts regulate CD44’s ability to bind hyaluronan in T cells, control the rolling adhesion of lymphocytes on vascular endothelial cells, and regulate hyaluronan- and CD44-mediated cancer cell migration." (PMID 26347743, 2015). "In order to validate that the isolated marker-positive cells were indeed cancer cells, we analyzed three CD44-captured EpCAMneg cells in comparison to one EpCAMpos CTC from the same patient for their somatic copy number profiles." (PMID 26695635, 2015). "Here, we assess the role of CD44 as a marker of cancer caner stem/progenitor cells in promoting EMT and matastasis in PCa carcinogenesis, and reveal a new potential therapeutic approach to battle PCa." (PMID 25483103, 2015). "In examining samples of NPCs, we found regions of CD44-positive cancer cells co-expressing the stem cell biomarker OCT4, suggesting the presence of CSCs." (PMID 26202311, 2015). "For example, metabolic modulation by CD44 has been demonstrated to contribute to antioxidant status in cancer cells." (PMID 26322272, 2015). "Supporting this notion, RNAi-directed downregulation of ADAM10 in cancer cells decreased the expression of cyclinD1, c-Myc and CD44." (PMID 26440150, 2015). "Growth inhibition in vitro and expression levels of the CD44 (cancer stem cell marker), cytokines, and growth factors were investigated after liposomal CDF treatment." (PMID 26098778, 2015). "Because the EMT is a predominant event driving cancer dissemination, the role of CD44 in this process merits further investigation." (PMID 25797261, 2015). "Much like CD44, the aldehyde dehydrogenase (ALDH) superfamily expression is also associated with CSCs and cancer progression." (PMID 25850653, 2015).